SMIM40 (small integral membrane protein 40)
Tractability: Antibody: UniProt predicts a signal peptide or a membrane-spanning region.
Gene: Protein-coding gene on chromosome 6 (33,323,628 to 33,329,279, reverse strand). Ensembl gene ENSG00000286920.
Subcellular location: Membrane
Gene Ontology:
Cellular component: membrane
Homologues: Orthologues: rabbit SMIM40 (84% identical), pig SMIM40 (80% identical), dog SMIM40 (78% identical), mouse Smim40 (76% identical), mouse Smim40-ps (73% identical), rat Smim40 (71% identical).